CHGA (chromogranin A)
Diseases named in the same sentence as CHGA in open-access papers (continued):
Sharing a sentence is not in itself a finding about the gene and the disease.
tumor (continued). "The gastropancreatic neuroendocrine neoplasms (GEP-NEN) are a heterogeneous group of tumours characterized by the expression of the neural antigens such as chromogranin A or synaptophysin." (PMID 25933800, 2015). "In our case, the tumor cells were positive for antibodies against the neuroendocrine markers chromogranin A, NCAM, and somatostatin receptor type 2." (PMID 25685590, 2015). "Physical examination and all biochemical laboratory results were within normal limits, including liver function tests, tumour markers (CA19-9, CEA, AFP, and CA15-3), and chromogranin A. Abdominal ultrasound showed an 8 cm tumour in liver segment IV." (PMID 26064749, 2015). "Immunohistologically, the tumor cells were positive for antibodies for the neuroendocrine markers, chromogranin A, neural cell adhesion molecule (NCAM), and somatostatin receptor type 2 (SSTR2)." (PMID 25685590, 2015). "The tumour was strongly and diffusely positive for chromogranin A. Three mitoses were present per 10 high power fields." (PMID 26064749, 2015). "The tumor cells were positive for chromogranin A, synaptophysin, CD99, cytokeratin 19, pan-cytokeratin and β-catenin, and also showed diffuse immunoreactivity for AFP and human chorionic gonadotrophin." (PMID 25886790, 2015). "This tumour entity is currently assessed by immunohistochemistry (IHC) detecting “general” NE markers such as chromogranin A (CHGA) and synaptophysin (SYP), but other markers have been considered as well." (PMID 24277232, 2014). "Chromogranin A as a tumour marker was shown to be significantly elevated, and it decreased with clinical improvement of the patient." (PMID 25520848, 2014). "Chromogranin A is another biochemical marker that correlates with tumor size, malignant potential, and is a marker for the rare SDHB-related PGL." (PMID 25298897, 2014). "Immunohistochemical staining revealed that the tumor cells were chromogranin A- and synaptophysin-positive, and carcinoembryonic antigen-, hepatocytic antigen- and α-fetoprotein-negative." (PMID 24944650, 2014). "One of 15 stained HER2 amplified carcinomas showed strong focal chromogranin A expression in only <1% of tumor cells and two of the 15 stained cases showed moderate to strong focal synaptophysin staining in <1% and <10% of tumor cells respectively." (PMID 24701575, 2014). "Of 18 stained cases 2 (11.1%) showed moderate to strong diffuse expression of chromogranin A in over 80% of tumor cells." (PMID 24701575, 2014). "Immunohistochemically >80% of the invasive tumor cells showed moderate granular chromogranin A expression and showed moderate membranous expression of CD117, whereas synaptophysin, NSE, and CD56 were negative." (PMID 24701575, 2014). "Immunohistochemically, the tumor cells were positive for chromogranin A, NSE, CD56, and pancytokeratin." (PMID 25314924, 2014). "The tumor often stains positive for neuroendocrine markers such as synaptophysin, CD 56, and chromogranin A." (PMID 25057271, 2014). "Tumor type was validated by immunostaining of chromogranin-A and synaptophysin expression and tumor grade was analyzed by Ki-67 proliferation index." (PMID 24915894, 2014). "Chromogranin A (CgA) was considered as the most practical and useful serum tumor marker in PNET patients." (PMID 25099181, 2014). "The tumor cells are stained positive for synaptophysin, chromogranin A, and neuron specific enolase (NSE)." (PMID 24062959, 2013). "Another option is a somatostatin analogue, such as octreotide, which reduces tumour number and size, reduces serum gastrin concentrations indirectly, and reduces circulating chromogranin A (CgA), which is a marker of ECL-cell mass and activity." (PMID 24098507, 2013). "A rosette-like structure was also observed with an extremely high rate of mitosis.Immunohistochemical analysis demonstrated that tumor cells were positive chromogranin A, synaptophysin, and CD56." (PMID 23653657, 2013).
tumor (continued). "Our immunohistochemical analysis revealed that the tumor was positive for Chromogranin A, vimentin, S-100, synaptophysin, thus providing a histopathological basis for a correct diagnosis of nonchromaffin paraganglioma of the retroperitoneum in the patient." (PMID 23537060, 2013). "Immunohistochemical expression of CD56, synaptophysin, and chromogranin A was strongly positive in the tumor cells." (PMID 24171129, 2013). "Several characteristic tumor cells were positive for chromogranin A, cluster of differentiation (CD) 56, Ki-67, and insulin-like growth factor (IGF)-II." (PMID 24307956, 2013). "Histological examination revealed a rosette arrangement of the tumor cells by HE staining and immunohistochemical study revealed positive CD 56, synaptophysin, and chromogranin A (LCNEC)." (PMID 23653657, 2013). "The tumor cells were positive for chromogranin A, synaptophysin, CD57, cytokeratin (Ck), and TTF1, but staining for CD 20 was negative." (PMID 23119202, 2012). "Double-labeling with fluorescent antibodies corroborated coexpression of SV40 TAg and CHGA in a large fraction of SV40 TAg-positive tumor cells in d30 and d60 tumors." (PMID 22253802, 2012). "All of the tumours were found to be diffusely positive for chromogranin A, synaptophysin and neuron-specific enolase with immunohistochemistry, confirming their neuroendocrine origin." (PMID 22476195, 2012). "Neuroendocrine differentiation of the tumor cells was confirmed in each instance by immunohistochemical analysis for neuron-specific enolase, chromogranin A, and/or synaptophysin and/or electron microscopy studies showing neurosecretory granules." (PMID 20205830, 2010). "Immunoperoxidase staining for chromogranin A, neuron specific enolase, and synaptophysin were positive in nearly 100% of the urethral tumor cells, showing a granular cytoplasmic distribution." (PMID 20205830, 2010). "The immunohistochemical reactivity for chromogranin A has been detected in 4% of RCC patients or the tumours have been wholly immunonegative for chromogranin A." (PMID 20462442, 2010). "In general, chromogranin A immunoreactivity was also observed in hypoxic tumor cells but the gradients in expression were less marked than NESP55." (PMID 20862257, 2010). "The aim of this study was to clarify the extent of the immunoexpression of NE markers, serotonin, CD56, NSE, chromogranin A and synaptophysin in RCCs and their significance regarding the behaviour of these tumours." (PMID 20462442, 2010). "A more traditional neuroendocrine feature in regions of tumor hypoxia was observed in tumors generated from SK-N-FI cells: in this tumor type chromogranin A expression was hypoxia-dependent, both at the protein and the transcriptional levels." (PMID 20862257, 2010). "Treatment with CHS 828 resulted in tumor regression (p < 0.001) and reduction in viable tumor fraction (p < 0.001) and metastatic spread (p < 0.05) in correlation with reduced plasma levels of the putative tumor marker chromogranin A (p < 0.001)." (PMID 19284605, 2009). "The ultrastructural immunohistochemistry showed that chromogranin A-positive cells had discoid and pleomorphic granules and were located in tumour nests or as single cells in the appendiceal wall." (PMID 18252007, 2008). "The endocrine cells in appendiceal tumour nests were chromogranin A-, somatostatin-, synaptophysin- (Figure." (PMID 18252007, 2008). "Plasma chromogranin A (CgA) has been claimed the most sensitive and specific marker of tumour volume." (PMID 16800893, 2006). "A total of 118 human endocrine and nonendocrine tumours were examined by immunocytochemistry, and compared to the expression of chromogranin A (CgA) in the same tumours." (PMID 12771991, 2003).
tumor (continued). "Immunohistochemical analysis disclosed positive staining to AE1/AE3, CK20, CK5/6, P40, c-kit and NCAM, and negative staining to CK-7, CK-8, AFP, GATA3, PSA, synaptophysin, and chromogranin A. Thus, the tumor of epithelial cell origin was confirmed through AE1/AE3 positive staining." (PMID 41515615, 2026). "However, this study demonstrated that xCT-positive tumor cells were neuroendocrine or at least neuroendocrine-like cells as they also expressed the neuroendocrine marker protein chromogranin A." (PMID 39869598, 2025). "By capturing viable CTCs, this platform can be extended to analyze other secretome markers in real time such as chromogranin A and cancer-specific proteases and cytokines, thereby allowing functional profiling and identification of phenotypic groups contributing to tumor heterogeneity." (PMID 40741917, 2025). "In the early stages, organoids were able to retain differentiated chromaffin cells, as indicated by metanephrine levels in culture supernatants that initially mirrored primary tumor patterns, as well as the expression of differentiation markers such as CHGA, SYP, and PNMT." (PMID 40576438, 2025). "A potential explanation for the alternate conclusion could be the lower sensitivity of chromogranin A, as we found that 37% of tumours with NED stained for synaptophysin only, in keeping with the known superior sensitivity of synaptophysin." (PMID 39526928, 2025). "Similarly, 14 years ago, the tumor cells exhibited positive staining for chromogranin A and synaptophysin." (PMID 40852171, 2025). "The diagnosis of NEC depends on histopathological recognition and reactivity to neuroendocrine markers such as synaptophysin, cytokeratin, and chromogranin A. The WHO classified tumor activity based on mitotic count and Ki‐67 proliferation index into NET G1, NET G2, NET G3, and NEC." (PMID 39894895, 2025). "Thus, although most NENs are positive for chromogranin A and synaptophysin: however, interpretation must always consider the degree of differentiation, histologic features, and biological behavior of the tumor." (PMID 41458541, 2025). "Neuroendocrine tumor marker levels (which may include serotonin, chromogranin A, neurokinin A, and pancreastatin) can suggest overall tumor burden and preoperative assessment provides a baseline for future comparison." (PMID 41082053, 2025). "European Society for Medical Oncology practice guidelines mandate histological diagnosis in all the patients and suggest the reporting of morphology, grading, and immunohistochemical staining of chromogranin A (cgA) and synaptophysin for appropriate pathological diagnosis of the tumor." (PMID 41235383, 2025). "Immunohistochemically, the tumor cells were positive for chromogranin A and synaptophysin." (PMID 40852171, 2025). "Besides the normalization of chromogranin A, insulin, and gastrin concentrations, an objective tumor response occurred in 10% of the cases, SD in 80% of the cases, and PD in 10% of the cases." (PMID 39996718, 2025). "Clinicians who encounter refractory or episodic hypertension in patients with known or suspected NSCLC should obtain plasma metanephrines and chromogranin A levels early, begin alpha-adrenergic blockade before any beta-blocker, and expedite oncologic staging to guide tumor-directed therapy." (PMID 40666573, 2025). "Additionally, dual immunofluorescence staining demonstrated co-expression of STMN1 and the NE marker Chromogranin A (CHGA) in NEPC cells scattered within an AdPC tumor exhibiting NE differentiation." (PMID 39776361, 2025). "Serum chromogranin A levels are also elevated and are useful in estimating the tumor burden." (PMID 39290926, 2024). "Apparently, CHGA, a typical NB-related protein, was exclusively expressed in tumor cells." (PMID 39228987, 2024).
tumor (continued). "After cellular annotation of the 6 tumour cell types based on marker gene expression, we were able to identify the following: C0 PSCA+ tumour cells, C1 CLDN7+ tumour cells, C2 UBE2C+ tumour cells, C3 MUC6+ tumour cells, C4 CHGA+ tumour cells and C5 MUC2+ tumour cells." (PMID 38894657, 2024). "However, TH was also specifically expressed in tumor areas, forming distinct islands (inferior block of IHC pictures, OC) matching the expression of the neuroendocrine marker ChgA." (PMID 39592661, 2024). "However, a histopathological examination revealed a small cell carcinoma, for a high nucleus-to-cytoplasm ratio in the tumor cells, as well as immunohistochemically positive findings for chromogranin A, and synaptophysin." (PMID 37721573, 2023). "One diagnostic method is to measure serum chromogranin A levels, but this is not a highly specific method for detecting this type of tumour." (PMID 37047829, 2023). "In addition, TMA verification studies with IHC assays confirmed that the expressions of UCH‐L1 and CHGA were significantly increased in tumour tissues of LNM stage III." (PMID 37246623, 2023). "Moreover, it has been shown that a small proportion of CRPC tumour cells acquire a neuroendocrine phenotype with neuronal marker expression, including chromogranin A (CHGA), synaptophysin (SYP) or enolase-2 (ENO2)." (PMID 37875732, 2023). "Synaptophysin and chromogranin A immunomarkers were strongly positive in all the tumours." (PMID 38239530, 2023). "The immunohistochemical examination also determines the expression of the granins, chromogranin A, B, and secretogranin II; however, depending on the location of the tumour, their expression may vary significantly." (PMID 37047829, 2023). "Tumor cell cluster 6 expressed neuroendocrine markers (e.g., CHGA and CHGB)." (PMID 36008377, 2022). "The other tumor observed from transplantation in the renal capsule (marker as RT) showed infiltrated cells into normal mice kidney tissue and the mouse was sacrificed 56 days after transplantation, which also expressed CHGA." (PMID 35954231, 2022). "In addition, the previous study reported that SPTs exhibit neuroendocrine differentiation and in these tumor tissues the author also observed chromogranin A, CA19-9, and vimentin which are used to diagnose pNENs." (PMID 36271376, 2022). "Since chromogranin-A normally resides in the membrane of neurosecretory granules, we studied the tumor tissue by electron microscopy to search for neurosecretory granules but could not identify any." (PMID 34228212, 2022). "Chromogranin A is a typical example of such a compound being specific for NE cells as it is found only in secretory granules and accordingly increased in persons with NE cell hyperplasia and NE tumours of low malignancy." (PMID 34948181, 2021). "With increased malignancy the tumour cells lose specific traits including expression of secretory granules, and chromogranin A in blood may fall despite increased mass of tumour cells." (PMID 34948181, 2021). "No relation was determined between the cut-off value of PLR and tumor localization, histological grade, mitosis, Ki-67 proliferation index, metastasis, lymphovascular invasion, perineural invasion, synaptophysin, and chromogranin A immunohistochemical staining (all p>0.05)." (PMID 34532190, 2021). "Monoanalyte tumor marker chromogranin A has a limited value for response assessment after PRRT." (PMID 33903926, 2021). "Five of these tumours expressed chromogranin A in their tumour cells when examined with immunohistochemistry with increased sensitivity by using tyramide signal amplification, which may suggest misclassification of neuroendocrine carcinomas as adenocarcinomas." (PMID 34948181, 2021). "The periodic monitoring of serum markers (like chromogranin A, neuron-specific enolase), circulating tumor cells, and circulating tumor DNA/RNA could aid in detecting the development of transdifferentiation or treatment resistance." (PMID 33754118, 2021).
tumor (continued). "They received four cycles of Lu-DOTATATE with encouraging results in terms of symptomatic control (decreased medication requirements), biochemical control (circulating chromogranin A), tumor response and general control of the disease with a median PFS of 29 months." (PMID 32664679, 2020). "IHC staining for chromogranin A and synaptophysin was also strongly positive in the tumor cells." (PMID 33031286, 2020). "We next hypothesized that patients with a higher tumor load according to elevated Chromogranin A (CgA) concentrations might display further decrease in miR-223 concentrations." (PMID 33382770, 2020). "In addition, several cell lines were also established from the primary tumor which we further characterized and found to have a similar cDNA profile like the tumor samples and express chromogranin A, B, as well as secretin and glucagon." (PMID 32373532, 2020). "Compared to control subjects, chromogranin A level was higher in the CgA+ group (p = 0.0086), thrombopoietin (p = 0.0040) and chromogranin B (p = 0.0070) in the CgA− group, while interleukin-6 was high in both tumor groups (p ≤ 0.0090)." (PMID 33383764, 2020). "Moreover, staining of the tumor was positive for chromogranin A and synaptophysin, which are neuroendocrine markers." (PMID 31678698, 2019). "All patient tumours were positive for chromogranin A, synaptophysin, serotonin, SSTR2 and Hsp90." (PMID 30730850, 2019). "Five tumours showed detectable levels of CHGA, a marker of neuroendocrine differentiation." (PMID 31537838, 2019). "On immunohistochemical staining, the tumor was positive for chromogranin A and synaptophysin." (PMID 30159830, 2018). "Tumour markers including chromogranin A were available for analysis in 85 patients." (PMID 29497803, 2018). "In addition, tumor cells in the liver were positive for chromogranin A and focally positive for HepPar-1." (PMID 29938394, 2018). "Tumor cells were positive for chromogranin A, synaptophysin, and CD56." (PMID 28744415, 2017). "Immunohistochemically, the tumor cells were positive for synaptophysin, chromogranin A, and CD56." (PMID 28895097, 2017). "An important diagnostic test that could suggest a GEP-NET is the analysis of serum chromogranin A. Chromogranin A is a protein found in the secretory granules of neuroendocrine cells, and its concentration correlates with tumor mass." (PMID 26919853, 2016). "Taken together, it is possible that cells marked jointly by Brachyury and ChgA might represent a population of cells within the tumour that can demonstrate CSC properties which include tumour aggressiveness, drug resistance, renewal, EMT and invasion." (PMID 26862851, 2016). "Tumor cells were positive for chromogranin A and glucagon, while insulin staining was negative." (PMID 27769070, 2016). "The tumour cells were positive for synaptophysin and focally positive for chromogranin A." (PMID 26955490, 2016). "The viable areas located at the periphery of the tumor contained numerous cells undergoing pyknosis, and the cytoplasm of these tumor cells was immunohistochemically positive for synaptophysin, tyrosine hydroxylase, and chromogranin A. The tumor cell nuclei were positive for SDHB." (PMID 27729064, 2016). "Immunoperoxidase staining for chromogranin A and synaptophysin was positive in all tumor tissues." (PMID 26124083, 2015). "A variety of prognostic factors has been described for patients with NETs including age, performance status, stage according to ENETS and AJCC, tumor load, levels of chromogranin A (CgA), presence of circulating tumor cells and grading based on the proliferation marker Ki-67." (PMID 26630134, 2015).